MAPK6 (mitogen-activated protein kinase 6)
Diseases named in the same sentence as MAPK6 in open-access papers (continued):
Sharing a sentence is not in itself a finding about the gene and the disease.
atherosclerosis (1 paper, 2025). A disease characterized by the build-up of fatty material and calcium deposition in the arterial wall resulting in partial or complete occlusion of the arterial lumen. "To preliminarily verify the anti‐inflammation effect of MAPK6 on atherosclerosis in humans, we applied sequencing data from human plaques and ultimately used scRNA‐seq, which can distinguish endothelial cells." (PMID 39763069, 2025). "Our study illuminates the advantages of MAPK6 in decelerating plaque progression, highlighting the potential of safeguarding MAPK6 as a novel therapeutic strategy against atherosclerosis." (PMID 39763069, 2025). "These insights substantially contribute to understanding the underlying mechanisms triggering atherosclerotic lesions in response to blood flow, offering promising avenues for targeted interventions focused on MAPK6 to prevent and treat atherosclerosis." (PMID 39763069, 2025). "AAV‐MAPK6, ApoE−/−MAPK6flox/floxTEKCre mice and the CXCL12 neutraligand were used to confirm the beneficial effects of MAPK6 against atherosclerosis." (PMID 39763069, 2025). "Previous studies revealed the involvement of MAPK6 in inflammation in the nervous system and cardiomyocytes, suggesting a potential role in atherosclerosis progression." (PMID 39763069, 2025). "To determine the function of MAPK6 in atherosclerosis, we transfected HUVECs with si‐NC or si‐MAPK6 and extracted RNA for comprehensive RNA sequencing analysis." (PMID 39763069, 2025). "The antagonistic effect of MAPK6 on inflammation underscore its potential as a therapeutic target for atherosclerosis, warranting further verification in the context of atherosclerosis." (PMID 39763069, 2025). "Endothelium‐specific MAPK6 overexpression exerts antiatherosclerotic effects in ApoE−/− mice, elucidating the unexplored role of MAPK6 in atherosclerosis." (PMID 39763069, 2025). "Taken together, the activation of the MAPK6‒TRIM21 ubiquitin‒proteasome complex in ECs following DSS stimulation promotes atherosclerosis by regulating endothelial inflammation through the EGR1/CXCL12 axis." (PMID 39763069, 2025). "The stark dichotomy observed in the role of MAPK6 between cancer and atherosclerosis highlights the nuanced and context‐dependent nature of its functions in distinct physiological processes." (PMID 39763069, 2025). "Moreover, we meta‐analysed publicly available single‐cell datasets to validate the role of endothelial MAPK6 in atherosclerosis and identify the regulatory role of MAPK6 in inflammation." (PMID 39763069, 2025). "Our RNA‐seq results and further experiments revealed that early growth response 1 (EGR1)/CXCL12 axis is the downstream effector of endothelial MAPK6 in DSS‐induced inflammation and atherosclerosis." (PMID 39763069, 2025). "In detail, the decrease in MAPK6 expression promotes the interaction between EGR1 and NF‐κB and ultimately accelerates the accumulation of NF‐κB in the nucleus, which promotes the transcription of CXCL12, thereby accelerating the progression of atherosclerosis." (PMID 39763069, 2025). "However, the precise relationship between MAPK6 and atherosclerosis has not been determined." (PMID 39763069, 2025).
colorectal cancer (1 paper, 2025). A primary or metastatic malignant neoplasm that affects the colon or rectum. "In T cells isolated from colorectal cancer, we have a similar pattern: The percentage of T cells expressing ERK3/MAPK6 and NLK is higher than the percentage of T cells expressing ERK4 (MAPK4) and ERK7/8 (MAPK15)." (PMID 39348153, 2025).
colorectal tumor (1 paper, 2024). "Taken together, RhoB, HIF1A, Met, MAPK6, and PKM may play key roles in promoting colorectal tumor formation in males." (PMID 38347027, 2024).
fibrosarcoma (1 paper, 2025). A malignant mesenchymal fibroblastic neoplasm affecting the soft tissue and bone. "Mitogen-activated protein kinase 6 (MAPK6) is a non-canonical MAPK, meaning it has unique activation mechanisms and does not follow the traditional rapidly accelerated fibrosarcoma (RAF)-MEK-ERK cascade." (PMID 40277902, 2025).
glioma (1 paper, 2025). A benign or malignant brain and spinal cord tumor that arises from glial cells (astrocytes, oligodendrocytes, ependymal cells). "Since MAPK6, HOXD8, and PSMB1 all belong to gene families with important roles in glioma, they remain considered targets for future evaluation as canine-specific drivers of HGO." (PMID 42135822, 2025). "There were several DEGs that were overexpressed in the French bulldogs that are not specifically implicated in glioma but belong to important gene families with known roles in glioma, including SCN11A, MAPK6, HOXD8, and PSMB1." (PMID 42135822, 2025).
head and neck cancer (1 paper, 2022). A primary or metastatic malignant neoplasm affecting the head and neck. "Similarly, MAPK6 promotes the migration of head and neck cancer cells." (PMID 34975321, 2022).
hepatocellular carcinoma (1 paper, 2020). A malignant tumor that arises from hepatocytes. "Similarly, in hepatocellular carcinoma (HCC), the microRNA was found to target MAPK6 to induce proliferation and migration of the cells." (PMID 32103099, 2020).
ischemia (1 paper, 2020). A hypoperfusion of the BLOOD through an organ or tissue caused by a PATHOLOGIC CONSTRICTION or obstruction of its BLOOD VESSELS, or an absence of BLOOD CIRCULATION. "In addition, miR-133a-5p is involved in the protective effect of propofol-mediated hepatic ischemia/reperfusion injury through targeting MAPK6." (PMID 32375631, 2020).
periodontitis (1 paper, 2023). An acute or chronic inflammatory process that affects the tissues that surround and support the teeth. "These were the periodontitis risk gene ABCA1, FBN2 (fibrillin 2), and MAPK6 (mitogen-activated protein kinase 6)." (PMID 37822091, 2023).
cancer (22 papers, 2015 to 2025). A tumor composed of atypical neoplastic, often pleomorphic cells that invade other tissues. "It has been found that MAPK6 is upregulated in BC and various other types of cancer, and knockdown of MAPK6 inhibits the proliferation, migration and invasion of cancer cells." (PMID 39823246, 2025). "Our study warrants future works to develop MAPK6-specific inhibitors and test their efficacy in treating human cancers, especially in combination therapy, such as that in combination with mTOR kinase inhibition." (PMID 34767444, 2021). "A comprehensive analysis of gene expression profiles of 10,152 patients in The Cancer Genome Atlas (TCGA) revealed that MAPK6 is expressed at varying levels in all cancer types." (PMID 34767444, 2021). "The limited numbers of previous studies on MAPK6 biology in human cancers have focused on regulation of the cancer cell migration/invasion/metastasis." (PMID 34767444, 2021). "In this large pan-cancer panel, survival was significantly decreased in the subset of patients above the 80th percentile of MAPK6 expression." (PMID 34767444, 2021). "This raises the prospect that blocking MAPK6, either alone or combined with mTOR inhibitors, will be an effective therapeutic for MAPK6-high cancers." (PMID 34767444, 2021). "In this study, we report that MAPK6 overexpression induces oncogenic outcomes, including transforming “normal” epithelial cells into anchorage-independent growth and enhancing cancer cell growth in an AKT-dependent manner." (PMID 34767444, 2021). "DNA microarray studies have produced inconsistent information about the regulation of MAPK6 expression in cancer." (PMID 34728718, 2021). "Accordingly, besides inhibiting growth, repressing MAPK6 also greatly sensitizes cancer cells to mTOR kinase blockade." (PMID 34767444, 2021). "NEAT1 again is competitively sponging miR‐98‐5p, where high miR‐98‐5p levels are inhibiting cancer cell growth, migration, and invasion on the one hand and reducing mitogen‐activated protein kinase 6 (MAPK6) levels on the other hand." (PMID 30430751, 2019). "MAPK6 has been found to be upregulated in breast and gastric cancer being responsible for promoted tumorigenesis in these cancer types." (PMID 30430751, 2019). "Previous studies on MAPK6 have focused predominantly on its implications in oncology, where both in vitro and in vivo studies have consistently underscored its role in enhancing the migration and invasion capabilities of cancer cells." (PMID 39763069, 2025). "This MAPK6-AKT pathway may provide a major route for cancer resistance to mTOR kinase inhibition, which may contribute to the lack of notable progress of using mTOR kinase inhibitors in the clinic." (PMID 34767444, 2021). "MAPK6 expression also correlated with AKT phosphorylation at S473 in human cancer tissues." (PMID 34767444, 2021). "Thus, MAPK6 function in human cancers, especially its role in regulating cancer growth, remains elusive." (PMID 34767444, 2021). "To date, it appears that whether MAPK6 executes tumor-promoting or tumor-suppressing function is cancer type or cancer cell context dependent." (PMID 34767444, 2021). "This raised the question of whether MAPK6 affects cancer cell sensitivity to mTOR kinase inhibition." (PMID 34767444, 2021). "In addition, MAPK6 has been connecting a series of signaling cascades and play a major role in the migration and invasiveness of certain types of cancers." (PMID 34728718, 2021). "The best-described tumor-promoting activity of MAPK6 is enhancing the migration/invasion/metastasis of cancer cells, including those of lung, head and neck, breast, and cervix, as well as the human umbilical vein endothelial cells (HUVECs) and vascular smooth muscle cells (VSMCs)." (PMID 34767444, 2021). "We conclude that MAPK6 can promote cancer by activating AKT and that targeting MAPK6, either alone or in combination with mTOR kinase blockade, may provide effective therapeutic approaches for cancer." (PMID 34767444, 2021).
cancer (continued). "MAPK6 is shown to be a key factor for organogenesis, cancer cell growth and invasiveness." (PMID 34728718, 2021). "In sharp contrast, our data support a growth-promoting role of MAPK6 in cancer cells." (PMID 34767444, 2021). "Collectively, these strongly support our identified MAPK6-AKT pathway in human cancers." (PMID 34767444, 2021). "Besides repressing growth, inhibiting MAPK6 sensitized cancer cells to mTOR kinase inhibitors." (PMID 34767444, 2021). "We demonstrated that MAPK6 overexpression transforms both human epithelial cell lines into anchorage-independent growth and also promotes growth, including anchorage-independent growth of all five cancer cell lines tested (PC3, DU145, SUM159, H1299, and OVCA433)." (PMID 34767444, 2021). "While the roles of canonical MAPKs, such as MAPK3/1 [extracellular signal–regulated kinase 1/2 (ERK1/2)], MAPK11-14 (p38β/γ/δ/α), and MAPK8-10 (c-Jun N-terminal kinase 1/2/3), are well established in carcinogenesis and tumor progression, the role of MAPK6 in human cancers remains unclear." (PMID 34767444, 2021). "MAPK6/MAPK4 signaling regulates cell morphology, migration, endocytosis, and cell cycle progression, and its dysregulation is a known marker of cancer." (PMID 37746266, 2023). "MAPK6, also named extracellular signal-regulated kinase 3 (ERK3), has been proven to be upregulated in multiple cancers and to promote cancer cell migration/invasion." (PMID 34975321, 2022). "Collectively, these data supported that MAPK6 and mTORC2 independently and coordinately promote AKT phosphorylation/activation and that MAPK6 emerges as a key regulator for cancer cells’ response to mTOR kinase blockade." (PMID 34767444, 2021). "Our data support an oncogenic and tumor-promoting activity of MAPK6 that predicts a negative correlation between MAPK6 expression and cancer patient survival." (PMID 34767444, 2021). "Therefore, we examined how MAPK6 affects PP242 and INK128 activities in repressing cancer cell growth." (PMID 34767444, 2021). "We conclude that MAPK6 can promote cancer by activating AKT independent of mTORC2 and targeting MAPK6, either alone or in combination with mTOR blockade, may be effective in cancers." (PMID 34767444, 2021). "Because MAPK6 has been reported in both the cytoplasm and the nucleus, it is expected that activation of cytoplasmic AKT will not be substantial in cancer cells where MAPK6 mainly locates in the nucleus." (PMID 34767444, 2021).
tumor (15 papers, 2010 to 2025). "The increased level of ROS causes overexpression of the gene encoding mitogen-activated protein kinase 6 (MAPK6), which leads to the creation of neoplasms." (PMID 36569285, 2022). "MAPK6 has been reported to exhibit tumor-promoting activities by enhancing tumor cell migration/invasion but not growth." (PMID 34767444, 2021). "AKT activity was required for MAPK6 oncogenic and tumor-promoting activities under the conditions that we examined." (PMID 34767444, 2021). "Since both the canonical PI3K/PDK1 pathway and our recently identified MAPK4 pathway can independently regulate AKT activation, the tumor-promoting activities of endogenous MAPK6 are likely to be context dependent." (PMID 34767444, 2021). "Together, these data strongly support an essential role for AKT activation in mediating the oncogenic and tumor-promoting activities of MAPK6." (PMID 34767444, 2021). "Dox-induced MAPK6 expression significantly promoted the growth, including the clonogenic growth and the anchorage-independent growth, of all these tumor cells." (PMID 34767444, 2021). "In addition, we also found that MAPK6 was highly expressed in tumor tissues, especially in the low ZNF671 group." (PMID 37215982, 2023). "MAPK6-AKT signaling promotes tumor growth and resistance to mTOR kinase inhibitors." (PMID 34767444, 2021). "Collectively, these data support a tumor-promoting role of MAPK6." (PMID 34767444, 2021). "Together, our data support a tumor growth–promoting function of MAPK6." (PMID 34767444, 2021). "Since MAPK4 can directly activate AKT to promote tumor growth, we examined whether MAPK6 also activates AKT." (PMID 34767444, 2021). "Previous studies have reported both tumor-promoting and tumor-inhibiting activities of MAPK6." (PMID 34767444, 2021). "Furthermore, in vivo experiments confirmed that overexpression of ZNF671 could inhibit tumor volume and weight, and down-regulate the expression of MAPK6." (PMID 37215982, 2023). "Furthermore, Rab31 knockdown impaired tumor growth and metastasis via MAPK6 in vivo." (PMID 34975321, 2022). "For liver tissue, relative to SKBR3 bearing tumor control, BPAF at 20 mg/kg bw/day significantly up-regulated the gene expression of four genes (MAPK3, MAPK6, EBP1, CCND1), whereas the mRNA relative levels of the other 15 genes had no a statistical difference." (PMID 36497816, 2022). "This supports the notion that MAPK6 and mTORC2 independently and coordinately phosphorylate AKT at S473 and indirectly at T308 for tumor-promoting effects." (PMID 34767444, 2021). "The reduced clonogenic growth of MDA-MB-231 herein may be attributed to the upregulation of some tumor suppressor proteins such as TSPAN6, MAPK6, SPRY2, HAUS4, stomatin (STOM) and conserved oligomeric golgi complex subunit 8 (COG8)." (PMID 38283944, 2023). "Furthermore, knockdown of MAPK6 greatly inhibited AKT phosphorylation and H1299 xenograft tumor growth, and overexpression of MAPK6 promoted AKT phosphorylation and PC3 xenograft tumors, demonstrating the tumor-promoting MAPK6-AKT pathway in vivo." (PMID 34767444, 2021).
infection (5 papers, 2017 to 2023). The state of being infected such as from the introduction of a foreign agent such as serum, vaccine, antigenic substance or organism. "BPMV infection induced MAPK6 in ‘L29’ plants, which, along with its encoded VSRs that suppress RNA silencing, increases the susceptibility of ‘L29’ plants to infection with G5H." (PMID 37099452, 2023). "The expressions of four other endogenous defense-related genes, viz., PAL, AOS2, NH1, MAPK6 were also found to be more enhanced upon pathogen infection in transgenic lines than that in their wild-type counterpart." (PMID 28801565, 2017). "In soybean, however, silencing MAPK6 rendered plants more resistant to infection with SMV." (PMID 37099452, 2023). "Finally, mitogen-activated protein kinase 6 (MA_10437020G0010), peroxidase, class IV chitinase and again, chalcone synthase genes showed a lower expression in the resistant genotype at early stages (7 dpi) of infection." (PMID 35692040, 2022). "The resistant ‘L29’ cultivar responded to G5H infection by activating MAPK3 at all tested time points, while MAPK6 was only activated at 1 hpi and then declined afterward." (PMID 37099452, 2023). "ZAT6 is also a target of mitogen-activated protein kinase 6 (MPK6), which can be activated by pathogen infection, indicating that plants may activate ZAT6-mediated defense responses at both the transcriptional and posttranslational levels." (PMID 36499767, 2022). "MAPK4 could not be detected in soybean following infection with either virus, which is in line with a previous finding that the separate application of SA or flagellin failed to induce MAPK4 in soybean but did induce MAPK6." (PMID 37099452, 2023).
MAPK6 also shares sentences with these, for which no sentence is quoted: gastric cancer (2 papers); mesothelioma (2); ovarian carcinoma (2); tongue squamous cell carcinoma (2); uveal melanoma (2); adenosquamous carcinoma (1); adrenocortical carcinoma (1); asthma (1); bacterial infection (1); brain tumors (1); cutaneous melanoma (1); dilated cardiomyopathy (1); head and neck tumor (1); Infertility (1); intrauterine growth restriction (1); leukemia (1); liver cancer (1); non-small cell lung carcinoma (1); Obesity (1); osteosarcoma (1); Parkinson (1); prostate carcinoma (1); pulmonary hypertension (1); Sepsis (1); triple-negative breast carcinoma (1).